WFDC2 (WAP four-disulfide core domain 2)
Description:
Plays a critical role in lung development (By similarity). Required for terminal differentiation of bronchiole club cells (By similarity). Required for development of airway barrier mechanisms, such as lamellar body formation in type II alveolar epithelial cells and cilia formation on ciliated epithelial cells following initiation of respiration at birth (By similarity). Required for type I alveolar epithelial cell and vascular endothelial development in the lungs, thereby mediating blood-air barrier exchange (By similarity).
Synonyms: HE4; WAP5; dJ461P17.6; EDDM4; BENP
Tractability: Antibody: UniProt places it where antibodies can reach, with high confidence; UniProt predicts a signal peptide or a membrane-spanning region; its Gene Ontology location is reachable by antibodies, with medium confidence.
Gene: Protein-coding gene on chromosome 20 (45,469,386 to 45,481,533, forward strand). Ensembl gene ENSG00000101443.
Subcellular location: Secreted
Pathways (Reactome):
Developmental Biology: Formation of the nephric duct
Gene Ontology:
Molecular function: aspartic-type endopeptidase inhibitor activity; protein binding; serine-type endopeptidase inhibitor activity; endopeptidase inhibitor activity; peptidase inhibitor activity
Biological process: antibacterial humoral response; club cell differentiation; innate immune response; lung vasculature development; positive regulation of lung alveolus development; positive regulation of lung ciliated cell differentiation; proteolysis; spermatogenesis
Cellular component: extracellular exosome; extracellular region
Genetic constraint (gnomAD): Loss-of-function variants: 8 observed, 9.66 expected, observed/expected ratio (o/e) 0.83, 90% interval 0.49 to 1.48. That is too few expected variants to judge how well the gene tolerates losing a copy. Missense variants: 166 observed, 147.5 expected, observed/expected ratio (o/e) 1.13, 90% interval 0.99 to 1.28. Synonymous variants: 74 observed, 62.57 expected, observed/expected ratio (o/e) 1.18, 90% interval 0.98 to 1.43.
Homologues: Orthologues: chimpanzee WFDC2 (100% identical), macaque WFDC2 (92% identical), pig WFDC2 (76% identical), mouse Wfdc2 (62% identical), guinea pig WFDC2 (61% identical), rat Wfdc2 (60% identical).
Diseases named in the same sentence as WFDC2 in open-access papers:
WFDC2 is named in the same sentence as 214 diseases in open-access papers, as found by Europe PMC text mining. Sharing a sentence is not in itself a finding about the gene and the disease. The quoted sentences say what the papers report.
ovarian carcinoma (463 papers, 2004 to 2026). A malignant neoplasm originating from the surface ovarian epithelium. "The WFDC2 gene, which encodes HE4, was silenced in the ovarian cancer cell lines OVCAR3 and OVCAR8 using shRNA." (PMID 41502510, 2025). "HE4, encoded by the WFDC2 gene, is a well-established biomarker for ovarian cancer diagnosis and monitoring, with elevated serum levels strongly correlating with poor clinical outcomes." (PMID 41502510, 2025). "WFDC2 is a secreted glycoprotein that was initially established as a diagnostic biomarker for ovarian cancer." (PMID 40723266, 2025). "In ovarian carcinoma, WFDC2 has emerged as a biomarker with high diagnostic accuracy across multiple clinical studies." (PMID 40350979, 2025). "Initially identified in the distal epithelium of the epididymis, where it likely functions as a protease inhibitor during sperm maturation, WFDC2 has gained prominence as a diagnostic biomarker for ovarian cancer." (PMID 40727473, 2025). "WFDC2 has been demonstrated to regulate the cytokine profile within the TME in ovarian cancer, promoting the polarization of tumor-associated macrophages toward the M2 phenotype while suppressing the infiltration and activation of NK cells and CD8+ T cells." (PMID 40727473, 2025). "HE4 is encoded by the WFDC2 gene, located at the locus of chromosome 20q12-13, the most frequently amplified genomic sequence in ovarian cancer, pointing to the role of this protein in tumourigenesis." (PMID 37238197, 2023). "Human epididymal protein 4 (HE4), a secreted glycoprotein encoded by the WFDC2 gene, is widely used as a tumor biomarker for ovarian cancer diagnosis in clinical practice." (PMID 37340055, 2023). "For example, Wfdc2 encodes the He4 protein, which has already shown significant clinical benefit in monitoring and diagnosing ovarian cancer." (PMID 36630696, 2022). "HE4, a small secretory N-linked glycoprotein (about 25 kDa), encoded by the WFDC2 gene, is another ovarian cancer marker intensely studied in the last several years and was recently introduced in clinical use." (PMID 36553184, 2022). "Serum HE4, also known as whey acidic four disulfide core domain protein 2 (WFDC2), encoded by the WFDC2 gene has been introduced for the routine diagnostics of ovarian cancer." (PMID 34452565, 2021). "It has been proven that WFDC2 promotes proliferation and metastasis in ovarian cancer, and serves as a diagnostic biomarker." (PMID 32678075, 2020). "WFDC2 is known to be overexpressed in ovarian carcinomas and encodes the HE4 protein, one of very few biomarkers used to monitor the disease in ovarian cancer patients." (PMID 28893231, 2017). "Genomic analysis of ovarian cancer identified gene amplification of the WFDC2 gene (that encodes the human epididymis protein 4 (HE4)) and the whey acidic protein gene loci in a large proportion of epithelial ovarian cancers." (PMID 26928556, 2016). "As compared with the markers used previously, it possesses increased sensitivity for detecting ovarian cancer, especially the stage I disease, whereas the HE4 encoding gene WFDC2 is expressed particularly in serous and endometrioid ovarian cancer." (PMID 19337252, 2009). "Although WAP four-disulfide core domain 2 (WFDC2) is widely recognized as a diagnostic biomarker for ovarian cancer, its function in other cancer types remains unclear." (PMID 40727473, 2025). "Moreover, the overexpression of WFDC2 is also associated with the proliferation, metastasis, and invasion of ovarian cancer, attributed to the change of several signaling pathways." (PMID 39296934, 2024). "Interestingly, WFDC2 has been extensively studied in ovarian cancer and widely used as a clinical diagnostic marker for ovarian cancer." (PMID 32678075, 2020). "Thus, the specific role of WFDC2 in cell growth in the microenvironment with high-dose estrogen may be associated with ovarian epithelial cancer cell growth and transformation, and may also be involved in TAM resistance." (PMID 26928556, 2016).
ovarian carcinoma (continued). "Furthermore immunohistochemical studies, coupled with molecular classification array experiments, have shown that re-expression of WFDC2 may be associated with specific types of ovarian cancers." (PMID 16600032, 2006). "Immunostaining of ascitic fluid has revealed high WFDC2 positivity in ovarian cancer (91%), whereas gastric and colorectal cancers exhibit lower positivity rates (25% and 21%, respectively)." (PMID 40727473, 2025). "Serum levels of the WFDC2 (HE4) protein have been widely investigated as a potential biomarker of ovarian cancers." (PMID 40362653, 2025). "Two proteins were associated with the risk of ovarian cancer, DKK4 and WFDC2 [1.46 (1.28–1.70), 1.57 (1.26–1.96)]." (PMID 38750076, 2024). "WFDC2 is overexpressed in ovarian cancer, particularly in endometrioid ovarian cancer, and interestingly, a current study reported WFDC2 and resectability in advanced epithelial ovarian cancer patients." (PMID 39296934, 2024). "WFDC2 is highly expressed in ovarian cancer, systemic sclerosis–related interstitial lung disease and lung adenocarcinoma." (PMID 36331721, 2023). "Human epididymis protein 4, a transcript of the WFDC2 gene on chromosome 20, is a relatively new serum biomarker for the detection of ovarian cancer." (PMID 36765633, 2023). "HE4 protein is encoded by the WAP four-disulfide core domain 2 (WFDC2), which was found to be highly expressed in ovarian carcinoma, especially in serous and endometrioid cancers." (PMID 35626367, 2022). "Additional biomarkers such as the WAP four-disulfide core domain 2 (WFDC2 or HE4) has been shown to increase the specificity in detection of ovarian cancer, especially in fertile women." (PMID 35406529, 2022). "Human epididymis protein 4 (HE4), also known as recombinant WAP four disulfide core domain protein 2 (WFDC2), is used as an ovarian cancer marker." (PMID 34065481, 2021). "HE4, also known as the whey acidic protein (WFDC2), is slightly less sensitive to the detection of early-stage ovarian cancer compared to CA-125 but it has better selectivity for distinguishing between malignant and benign pelvic masses." (PMID 34944963, 2021). "WAP four-disulfide core domain 2 (WFDC2) is a small secretory protein that has been widely studied in ovarian cancer." (PMID 32678075, 2020). "Gene functional analysis demonstrated that up-regulated WFDC2 and INAVA promoted ovarian cancer cell migration, WFDC2 enhanced cell proliferation, while down-regulated AOX1 was functional in inducing cell apoptosis of ovarian cancer." (PMID 33135729, 2020). "It has been reported that WFDC2 is involved in epithelial–mesenchymal transformation, and this gene is highly expressed in epithelial ovarian cancer than in normal epithelial cells." (PMID 33135729, 2020). "Some of the proteins in the 11-protein panel, aside from MUCIN-16 and WFDC2 (HE4), have previously been associated to ovarian cancer." (PMID 31240259, 2019). "We finally added three proteins (WFDC2, KRT19, and FR-alpha) based on their previous association with ovarian cancer stages I–II in our modeling, or in the previous literature." (PMID 31240259, 2019). "Human epididymis protein 4 (HE4), encoded by the WFDC2 gene and also known as WAP four-disulfide core domain protein 2 (WFDC2), was first introduced as a potential ovarian cancer biomarker in 2003." (PMID 29484129, 2018). "WFDC2 has been shown to be a biomarker for ovarian cancer and overexpression promotes ovarian tumor growth." (PMID 30383866, 2018). "HE4 protein is encoded by WAP four-disulfide core domain 2 (WFDC2), which was found to be highly expressed in ovarian carcinoma, especially in serous and endometrioid cancers." (PMID 28039447, 2017). "Our results demonstrated that pharmacological concentrations of estrogen induced apoptosis in human ovarian cancer cells that involved WFDC2 expression." (PMID 26928556, 2016).
ovarian carcinoma (continued). "WAP four-disulfide core domain protein 2 (WFDC2) shows a tumor-restricted upregulated pattern of expression in ovarian cancer." (PMID 26928556, 2016). "The suppression of the endogenous WFDC2 in ovarian cancer cells not only inhibited cell growth, but also significantly strengthened the response of estrogen-insensitive SKOV3 cells to estrogen." (PMID 26928556, 2016). "This study also provides the first evidence for a functional role of the WFDC2 gene in the estrogen-dependent proliferation of ovarian cancer cells." (PMID 26928556, 2016). "The focus of our upcoming research, therefore, will be to gain a better understanding of the relationship between WFDC2 and the insulin-like growth factor pathway to ascertain the role of WFDC2 on the physiological and pathological behavior of ovarian cancer." (PMID 26928556, 2016). "Given that WFDC2 knockdown transformed a hormone-unresponsive ovarian cancer cell line in an estrogen-responsive one, we were eager to know how this would be reflected at the gene expression level." (PMID 26928556, 2016). "WFDC2 knockdown decreased proliferation of SKOV3 ovarian cancer cells and, more strikingly, switched on a strong estrogen response in this estrogen-unresponsive cell line." (PMID 26928556, 2016). "This is a known biomarker for ovarian carcinoma, and WFDC2 protein was identified in tumor tissue, urine, and serum." (PMID 26317775, 2015). "Expression of human epididymis protein HE4 (WFDC2) in ovarian cancer was initially reported in 1999, and subsequently defined as a biological marker of ovarian cancer in 2003." (PMID 23894390, 2013). "Certain genes are well-known biomarkers in particular cancers, including BRCA1 and BRCA2 in breast cancer, PSA in prostate cancer and WFDC2 in ovarian cancer." (PMID 24137416, 2013). "Hereby, GAS6 is roughly in the middle of this top candidate group, where also well-known ovarian cancer markers like HE4 (WFDC2) or DDR1 are listed." (PMID 23878800, 2013). "As a component of the disulfide-core protein group, the WFDC2 (HE4) gene is also elevated in ovarian cancer." (PMID 21577260, 2011). "The mRNA expression of genes encoding HE4 and CA125, namely WFDC2 and MUC16, respectively, was also analysed in the tissue specimens of various types of endometriosis, ovarian cancer, endometrial cancer, and normal endometrium." (PMID 19337252, 2009). "The expression of WFDC2 was significantly (P<0.05) higher in ovarian cancer (median of log2 intensity value 9.25) than in the ovarian endometrioma (6.73) with fold change (FC) of 5.7." (PMID 19337252, 2009). "Recent studies have also shown that WFDC2 protein is overexpressed in some types of ovarian cancer, principally serous and endometrioid tumours." (PMID 16600032, 2006). "This antibody has previously been used for both immunohistochemical analysis of WFDC2 in ovarian cancers as well as in ELISAs." (PMID 16600032, 2006). "In addition to ovarian cancer, increased WFDC2 expression has been reported in lung cancer, suggesting its broader applicability in cancer diagnosis and management." (PMID 40727473, 2025). "HE4 is encoded by gene WFDC2 and is overexpressed in ovarian cancer." (PMID 40385783, 2025). "WFDC2 (whey acidic protein four-disulfide core domain 2, also known as human epididymis protein 4 [HE4]), initially recognized as a biomarker of ovarian cancer, has recently attracted considerable attention because of its elevated expression in lung adenocarcinoma (LUAD) and other malignancies." (PMID 40723266, 2025). "Besides, histone deacetylase 3 (HDAC3) is overexpressed in ovarian cancer, inducing the WFDC2 expression and binding to it." (PMID 39296934, 2024). "WFDC2 has also been extensively studied for ovarian cancer diagnosis." (PMID 39296934, 2024). "In fact, WFDC2, which encodes the protein HE4, has been shown to correlate with poor survival in HGSC patients and promote tumor growth and confer chemoresistance in ovarian cancer." (PMID 33917869, 2021).
ovarian carcinoma (continued). "Previous studies have identified multiple markers of potential drug targets that may help improve the survival rate of ovarian carcinoma patients such as WFDC2, CA125 and MSLN14–16." (PMID 34001978, 2021). "As a cancer-specific gene, several hormone-response elements were found within the WFDC2 promoter, including an estrogen response element (ERE) and RORA, which may be attributed to HE4 upregulation in ovarian cancer and ovarian cancer specificity." (PMID 26928556, 2016). "We postulate that increased WFDC2 expression plays an important role in altering the estrogen pathway in ovarian cancer, and the identification of WFDC2 as a new player in endocrine-related cancer encourages further studies on the significance of this gene in cancer development and therapy." (PMID 26928556, 2016). "Therefore, we compared the growth of HO8910-209 or SKOV3-209 cells with the negative control clone of each cell line to determine the role of WFDC2 both in estrogen-sensitive and estrogen-insensitive ovarian cancer cells." (PMID 26928556, 2016). "Thus, knockdown of WFDC2 expression in ovarian cancer cells increased cell apoptosis induced by high-dose E2 in both estrogen-sensitive and estrogen-insensitive cells." (PMID 26928556, 2016). "The suppression of the endogenous WFDC2 in ovarian cancer cells was more likely suppressed by TAM." (PMID 26928556, 2016). "In this study, we undertook to prove the hypothesis that WFDC2 is regulated by estrogen and that it might play a role in tumorigenesis induced by estrogen in ovarian cancer." (PMID 26928556, 2016). "Additional studies of WFDC2 could provide significant information as to its potential pathophysiological actions in ovarian cancer progression and might lead to novel strategies for tumor treatment in patients treated with anti-estrogens." (PMID 26928556, 2016). "The alternative expression levels of these genes in certain organs may act as an indicator of cancer development, including WFDC2 in ovarian cancer, ADAM29 and ADAM7 in melanoma and Eppin in prostate cancer." (PMID 24137416, 2013). "Certain genes are well-known to be specifically expressed in certain cancers, including WFDC2, which is uniquely-expressed in ovarian tumors and may be a promising marker in the diagnosis of ovarian carcinoma." (PMID 24137416, 2013). "The performance of the MUC16/WFDC2 combination marker clearly varied with ovarian cancer histology: the percentage of cases correctly classified was 86% (38/44) for serous cases, 83% (5/6) for endometrioid cases, 17% (1/6) for mucinous cases and 0% (0/5) for clear cell cases." (PMID 18612378, 2008). "At the same time, related studies have found that the HE4‐encoding gene WFDC2 can induce the expression of matrix metalloproteinase 2 (MMP2) by activating the AKT signaling pathway, promote epithelial–mesenchymal transition, and then promote the metastasis of ovarian cancer cells." (PMID 38742362, 2024). "Human epididymis protein 4 (HE4), which is encoded by the WAP four‐disulfide core domain 2 gene, was approved by the US Food and Drug Administration in 2008 for the early diagnosis, efficacy evaluation, and relapse monitoring of patients with epithelial ovarian cancer." (PMID 33934540, 2021). "Interestingly, we found that WFDC2 is downregulated in prostate cancer compared to ovarian cancer." (PMID 32678075, 2020). "Thus, targeted screening for WFDC2 protein inhibition might benefits for the treatment of ovarian cancer." (PMID 33135729, 2020). "Moreover, serum levels of WFDC2 are indicative of ovarian cancer." (PMID 29713252, 2018). "Thus, the results indicated that knockdown of WFDC2 not only increased the sensitivity of ovarian cancer cells to the growth inhibition induced by high-dose E2, but also transformed the estrogen-unresponsive SKOV3 cells from a hormone-independent to an estrogen-responsive phenotype." (PMID 26928556, 2016).